BCAT1 (branched chain amino acid transaminase 1)
Diseases named in the same sentence as BCAT1 in open-access papers (continued):
Sharing a sentence is not in itself a finding about the gene and the disease.
tumor (continued). "Regardless of the underlying mechanisms, BCAT1 and CD133 have been proposed to be involved in the tumour metabolism and progression, eventually leading to cancer recurrence and even death." (PMID 32571264, 2020). "Similarly, when Bcat1-null nonsmall lung carcinoma (NSCLC) cells were implanted subcutaneously in mice, these cells displayed impaired tumor-forming ability [12▪]." (PMID 29211698, 2018). "BCAT1 was previously found to be highly expressed in tumors carrying non-mutated IDH1/2 alleles, where it promoted tumor cell proliferation and invasiveness." (PMID 29502308, 2018). "The tumor volume increased after bevacizumab treatment in both IDH1 WT and BCAT1 sh#1 rats." (PMID 27626306, 2016). "Before the treatment, the tumor volume of BCAT1 sh#1 rats was smaller than IDH1 WT rats at initial without statistical significance (9.64 mm3 [IQR, 7.70–32.28] vs 27.77 mm3 [21.12–45.15]; p = 0.1797)." (PMID 27626306, 2016). "BCAT1 sh#1, in contrast, blocked the BCAA catabolism by interfering with tumor energy production and macromolecule synthesis, and accommodated anti-angiogenic therapy by reducing tumor glutamate excretion." (PMID 27626306, 2016). "The tumor cell proliferation and vascularity, which were evaluated by KI-67 and CD34, respectively, were markedly decreased in BCAT1 sh#1 rats than IDH1 WT rats (5.48% [IQR,–0.04–11.00] vs 33.86% [23.56–44.18]; p = 0.0001, and 1.22% [IQR, 0.71–1.72] vs 5.20% [2.44–7.95]; p = 0.0044, respectively)." (PMID 27626306, 2016). "BCAT1 and IKZF1 are both involved in tumour growth and invasiveness." (PMID 25928810, 2015). "BCAT1 suppression in SKOV3 cells led to the induction of several gene nodes (EIF5A2, EIF5 and EIF4H), as part of the eukaryotic initiation factors (eIFs) network, shown to display all elements of a complete oncogenic, as well as tumor suppressive cascade." (PMID 26372729, 2015). "However, not every type of cancer is characterized by overexpression of BCAT1, and suppression of BCAT1 inhibits proliferation in not all types of tumor." (PMID 40723225, 2025). "Thus, BCAT1, BCAT2, and BCKDK have emerged as potential therapeutic targets for tumor treatment." (PMID 40723225, 2025). "Immunoblotting and staining verified that overexpression of HuR was followed by the upregulation of BCAT1 expression in CRPC cell lines and clinical CRPC tissues, and genetic modification further confirmed that HuR knockout decreased BCAT1 expression in CRPC cells and tumour xenografts." (PMID 38369471, 2024). "Moreover, our investigation clearly showed the therapeutic potential of KH-3 in CRPC in vitro and in vivo, which is closely related to a decrease in BCAT1 expression and ERK5 activation, which is consistent with the idea that suppressing BCAT1 can inhibit tumour development." (PMID 38369471, 2024). "Consistent results were obtained from the tumour xenograft model, and BCAT1 overexpression in HuR KO1 cells significantly accelerated the growth of the xenograft tumours compared to the growth of the xenograft tumours derived from HuR KO1 cells without BCAT1 overexpression." (PMID 38369471, 2024). "However, BCAT1 and BCAT2 were upregulated in tumours in our cohort and GSE26566." (PMID 37076565, 2023). "Hence, tumor genotyping is not required if these two methylation biomarkers are used for ctDNA detection, and testing for methylated BCAT1/IKZF1 ctDNA is unlikely to be confounded by tumor heterogeneity or clonal drift following adjuvant therapy." (PMID 35822405, 2023). "In contrast, BCAT1 inhibitors did not exhibit significant anti‐tumour efficacy in CLL." (PMID 35811334, 2022). "However, BCAT1 DNA methylation levels were significantly higher (p < 0.001) in tumor samples as compared with non-tumoral controls." (PMID 36123616, 2022). "Similarly, PDAC and non–small cell lung carcinoma (NSCLC) obtain BCAAs as a nitrogen source, whereas deletion of BCAT1 and BCAT2 could prevent NSCLC tumor formation in vivo but has limited effect on PDAC tumor growth." (PMID 33882453, 2021).
tumor (continued). "BCAT1 expression was found to be associated with the TIL level, histological grade, and the Ki67 index but not with criteria such as the age, lymphovascular invasion, tumour size, axillary lymph node status, and pathological stage." (PMID 32571264, 2020). "Silencing of BCAT1 in cells has not shown tumor regression of xenograft." (PMID 33488950, 2020). "Thus, not all cancer types express high levels of BCAT1 and suppression of BCAT1 does not always correspond to a decrease in tumor size." (PMID 29211698, 2018). "In conclusion, we have shown that BCAT1 is significantly overexpressed in LMP tumors and HG serous EOC tumors compared to normal ovarian tissues, as epigenetic mechanisms (DNA hypomethylation) could be involved in BCAT1 overexpression in this tumor type." (PMID 26372729, 2015). "However, Mayers and colleagues found decreased SLC7A5, BCAT1, BCAT2 and BCKDH expression in PDAC tissue, and loss of BCAT2 does not affect PDAC tumor formation." (PMID 33882453, 2021). "In all patients and IDH1-wildtype group, the tumor volume and mean ADC value based of FLAIR images had a significant negative correlation with BCAT1 expression, which was observed independently with IDH1 mutation status." (PMID 29255149, 2017). "The possible reason for this is the extremely low expression of BCAT1 in tumor tissues of DEN and CCl4-induced HCC mouse models, suggesting that DEN and CCl4-induced HCC mouse models are more suitable for the study of BCAT2 rather than BCAT1 in HCC." (PMID 38580754, 2024). "The expression of BCAT1 (data not shown), the branched chain amino acid transaminase, correlated significantly with leucine and isoleucine concentration and was significantly higher in the SHH tumours." (PMID 38184938, 2024). "However, some studies reported that BCAT1 and BCAT2 are not involved in human cancers such as PDAC because these enzymes can not induce PDAC tumor formation." (PMID 37637065, 2023). "Furthermore, this study identified a high-BCAT1- and high-CD133-expression subset of patients with TNBC, who had significantly worse prognoses in the cases of both basal-like and non-basal-like tumours." (PMID 32571264, 2020). "The fluorescent orthotopic tumour xenograft model revealed that BCAT1 overexpression in HuR KO1 cells markedly increased the size of the xenograft tumours and metastatic lesions compared to those in mice inoculated with HuR KO1 cells without BCAT1 overexpression." (PMID 38369471, 2024).
cancer (119 papers, 2008 to 2026). A tumor composed of atypical neoplastic, often pleomorphic cells that invade other tissues. "BCAT1 has been reported to be highly expressed in a variety of cancers and to be associated with poor progression and prognosis." (PMID 39324007, 2024). "Elevated BCAT1 expression is commonly observed and is associated with lower rates of survival in patients with various types of cancer." (PMID 39795113, 2024). "For stromal-rich PDAC, cancer-associated fibroblasts (CAFs) provide BCKAs through BCAT1-mediated BCAA catabolism to fuel cancer cells." (PMID 38632504, 2024). "Since activated RhoC controls cytoskeletal dynamics, this finding exposes a novel function of BCAT1 concerning the direct regulation of cancer cell dynamics and association with malignant phenotypes." (PMID 39795113, 2024). "MSI2, an oncogenic RNA-binding protein, is associated with the BCAT1 transcript and positively regulates its protein levels in those cancers." (PMID 37076565, 2023). "Upregulation of BCAT1 has been observed in various cancers, where in some cases it has been linked to increased cell proliferation and invasion." (PMID 37885806, 2023). "Taking COAD as an example, it had the most BCAT1 mutations among the 32 cancers included in our study, and interestingly, BCAT1 expression was negatively relevant to the expression of an MMR gene––EPCAM." (PMID 34984849, 2022). "In stroma-rich pancreatic cancers, elevated BCAT1 protein levels in cancer-associated fibroblast (CAF) cells led to an increase in secreted BCKA, fueling PDAC cell growth by maintenance of downstream metabolite pools." (PMID 35663242, 2022). "This analysis revealed that higher BCAT1 values were associated with a significant increase in the risk of having cancer (adjusted OR = 2.36, 95% CI [1.18, 5.71], p = 0.031)." (PMID 36123616, 2022). "BCAT1 catalyzes the catabolism of branched-chain amino acids (BCAAs), and the association of BCAAs with different cancer phenotypes has been demonstrated in a series of studies." (PMID 35574395, 2022). "BCAT1 in particular is associated with cancer cell growth and has been proposed as a prognostic cell marker." (PMID 35155562, 2021). "Utilizing in vitro assays of cell migration, we further demonstrated that increased cancer cell progression is mechanistically linked to BCAT1-mediated regulation of SOX2 expression." (PMID 34646394, 2021). "Specifically, BCAT1 expression has been implicated in cancer growth, with suppression of BCAT1 limiting proliferation." (PMID 33946927, 2021). "The phosphoserine aminotransferase 1 (PSAT1) and branched-chain amino acid transaminase 1 (BCAT1) were upregulated in many carcinoma tissues and associated with cell proliferation." (PMID 32509585, 2020). "Branched-chain aminotransferase 1 (BCAT1), which converts BCAAs to the corresponding branched-chain α-keto acids, has been implicated in cancer growth." (PMID 31409769, 2019). "Using the TISIDB database, we investigated the correlation between BCAT1 expression and various immune cell infiltrations based on pan-cancer samples, and found that BCAT1 was closely associated with various immune cell infiltrations in most cancers." (PMID 39324007, 2024). "BCAT1 is overexpressed in multiple cancer types, causing malignant phenotypes and a poor prognosis." (PMID 37460470, 2023). "Interestingly, BCAT1 expression was associated with at least six immune checkpoint genes in 32 cancers, while all 46 immune checkpoint genes were detected as relevant to BCAT1 expression in at least eight cancers." (PMID 34984849, 2022). "In addition, some studies reported that BCAT1 was a target gene of miR-218, and in this capacity, it was associated with the proliferation, spread and invasion of cancer cells." (PMID 36119495, 2022). "In addition, other studies report high BCAT1 expression was associated with poor patient survival in several types of cancer." (PMID 35318805, 2022).
cancer (continued). "In addition, many studies have explored BCAT1 as a potential target for cancer therapeutics, as it is also linked to cell proliferation via m-Torc1 activity." (PMID 35155562, 2021). "BCAT1 is mainly involved in regulating the occurrence and development of cancer, while BCAT2 mainly plays a role in metabolic diseases." (PMID 41503231, 2026). "A framework is presented to categorize the differential reliance of various cancers on key catabolic enzymes-BCAT1, BCAT2 and BCKDK-underscoring their therapeutic vulnerability." (PMID 41769003, 2026). "Branched-chain amino acid aminotransferases (BCATs), existing as the two isoforms BCAT1 and BCAT2, are responsible for the catabolism of branched-chain amino acids (BCAAs) and are highly upregulated and implicated in a diverse range of cancers." (PMID 40005214, 2025). "By increasing BCAT1, cancer cells rapidly transaminate imported BCAAs, impacting multiple downstream processes." (PMID 41502503, 2025). "Knockdown of BCAT1 has been shown to repress growth, supporting its significance in cancer progression." (PMID 40066850, 2025). "BCAT1 is normally enriched in neural and germinal tissues but is ectopically expressed in various cancers, whereas BCAT2 is broadly expressed in adult tissues and resides in the mitochondria of many cell types." (PMID 41502503, 2025). "Targeting BCAT1 has been demonstrated to improve cancer vaccination and immune checkpoint blockade by preventing IFNγ-induced CSC modification." (PMID 40438606, 2025). "Inhibiting BCAT1 by Eupalinolide B or the anti-cancer drug doxycycline reduces intracellular BCAA or BCKA levels, respectively." (PMID 40507232, 2025). "Inhibiting BCAA metabolism (such as using BCAT1 inhibitors) can reverse resistance and enhance cancer cells’ sensitivity to chemotherapy, targeted therapy, and immunotherapy." (PMID 40438606, 2025). "Like all other cancers, deletion, inhibition, or increased degradation of BCAT1 increases apoptosis and decreases proliferation." (PMID 40507232, 2025). "In cancers with overexpression of BCAT1, studies have shown that intracellular BCAAs accumulate, accompanied by a reduction in the expression of downstream enzymes." (PMID 40507232, 2025). "At the subcellular level, BCAT1 (cytosol, upregulated in many cancers) accelerates cytosolic transamination to generate glutamate and BCKAs, while BCAT2 (mitochondria) supports coupling of transamination to mitochondrial oxidation." (PMID 41502503, 2025). "Normally low in breast tissue, BCAT1 is frequently elevated in breast tumors, especially more advanced or basal-like cancers." (PMID 41502503, 2025). "Real-time quantitative PCR (RT-qPCR) was employed to analyze differential expression of branched-chain amino acid transaminase 1 (BCAT1) between cancer and paracancer tissues and between different cell lines." (PMID 38309289, 2024). "Targeting BCAT1 to reduce its expression has been shown to inhibit metastatic spread and alter the behavior of cancer cells, implicating the modulation of factors such as SOX2 in cancer progression." (PMID 38607736, 2024). "BCAT1 is highly expressed in a variety of cancers, promotes cancer cell migration and invasion, and has received much attention in recent years." (PMID 39324007, 2024). "In breast cancer, elevated BCAT1 levels promote mitochondrial biogenesis in an mTOR-dependent manner, which supports cancer proliferation." (PMID 39795113, 2024). "Studies have indicated that BCAT1 overexpression is positively correlated with cancer progression and poor outcomes." (PMID 38369471, 2024). "Despite advances in understanding the molecular underpinnings of various cancers, the role of branched-chain amino acid transferase 1 (BCAT1) in KIRC remains underexplored." (PMID 39324007, 2024). "Recent reports substantiate the close relationship between BCAT1 expression and mTOR signaling activity in other cancers." (PMID 38309289, 2024).
cancer (continued). "The one upregulated gene was BCAT1 (5.3×), which catalyzes the only step in BCAA degradation that occurs outside of the mitochondria, and is the major isoform implicated in cancer growth." (PMID 39000280, 2024). "Developing BCAT1-targeting therapies holds promise not only for treating KIRC but also for other cancers where BCAT1 plays a critical role." (PMID 39324007, 2024). "Currently, BCAT1 has been proposed as a prognostic marker for a variety of cancer types and has multiple functions in cancer growth and progression." (PMID 39324007, 2024). "We traversed the literature and observed that BCAT1 is significantly upregulated during progression of various types of cancer and has emerged as an essential biomarker, but its role in KIRC is poorly understood." (PMID 39324007, 2024). "Further, BCAAs have been implicated in sustaining T-cell activation, with changes in BCAA metabolism in different cancers being largely due to BCAT1 overexpression." (PMID 38928249, 2024). "In acute myeloid leukemia stem cells, BCAT1 restricts α-ketoglutarate levels and induces DNA hypermethylation, thereby maintaining cancer stem cell function." (PMID 39075053, 2024). "Increasing evidence implicates BCAT1 as a promising drug target for cancer therapy, yet the discovery of effective BCAT1 inhibitors remains limited." (PMID 39143065, 2024). "BCAT2 is expressed widely in human tissues, while BCAT1 is highest in brain, kidney, and upregulated with cancer progression." (PMID 37918802, 2023). "BCAT1 is overexpressed in many cancers and has been proposed as a marker for predicting cancer prognosis." (PMID 37704698, 2023). "BCAT1 redox function maintains cell mitosis, which is essential for chromosome separation, and provides an explanation for BCAT1’s role in promoting cancer cell proliferation." (PMID 38028625, 2023). "One gene of interest that has been extensively studied in the context of cancer, BCAT1, is also involved in glutamate metabolism in excitatory neurons in the cerebral cortex." (PMID 37344908, 2023). "For instance, we failed to collect enough body fluid samples to verify the expression of BCAT1 in pan‐cancer." (PMID 34984849, 2022). "AUC values were greater than 0.7 in 8/20 cancers, suggesting that BCAT1 expression demonstrated the conspicuous ability to distinguish these cancers tissues from their normal tissues." (PMID 34984849, 2022). "Cox analyses and Kaplan‐Meier curves were utilized to identify the prognosis significance of BCAT1 expression in cancers." (PMID 34984849, 2022). "Upregulated BCAT1 expression represents poor prognosis of cancers patients, and it serves as a potential marker for cancer immunotherapy." (PMID 34984849, 2022). "The differential expression of BCAT1 in cancers is common, and its elevated expression is predominant." (PMID 34984849, 2022). "This study revealed TGF-β and BCAT1 as feasible therapeutic targets in PDAC by abrogating BCKA nutrient transfer from CAFs to cancer cells." (PMID 36115986, 2022). "Recent data report that BCAT1 expression is highly expressed in multiple cancers and required for individual cancer progression." (PMID 35318805, 2022). "In our study, upregulated BCAT1 expression was identified in 10 cancers (e.g., BRCA), while decreased BCAT1 expression was detected in LUSC." (PMID 34984849, 2022). "The results revealed that BCAT1 expression represented unfavorable progression (e.g., recurrence) in patients with these cancers." (PMID 34984849, 2022). "A Kruskal–Wallis test and the Wilcoxon rank‐sum and signed‐rank tests were applied to investigate diverse BCAT1 expression between various groups (e.g., cancer tissues versus normal tissues)." (PMID 34984849, 2022). "For the first time, the research comprehensively demonstrates over‐expression of BCAT1 in pan‐cancer, which improves the understanding of the pathogenesis of BCAT1 in pan‐cancer." (PMID 34984849, 2022).